TH (tyrosine hydroxylase)
Diseases named in the same sentence as TH in open-access papers (continued):
Sharing a sentence is not in itself a finding about the gene and the disease.
tumor (continued). "Alk‐F1178S animals were bred with Th‐MYCN transgenic mice expressing MYCN under the control of the tyrosine hydroxylase (Th) promoter, and tumour development was followed." (PMID 33411331, 2021). "We then proceeded to explore and found that knockdown of either TH or DRD5 would prohibit the proliferation of tumor cells, emphasizing the importance of dopamine pathway in EC." (PMID 33898321, 2021). "We have found that TH, the synthetase of dopamine, was overexpressed in tumor tissues, especially those with lymphatic metastasis." (PMID 33898321, 2021). "The results have demonstrated that the degrading enzymes of dopamine were significantly downregulated in EC tumor, while TH presented significantly higher expression in tumor tissues." (PMID 33898321, 2021). "The substituents were further utilized to form the corresponding TH analogs (Ethyl-TH, Isopropyl-TH and Butyl-TH), making them easier to protonate for positive charge in acidic tumor microenvironments." (PMID 28603674, 2017). "The pH-sensitive, cell penetrating ability of TH makes it suitable for targeted drug delivery to tumor cells with an acidic extracellular environment." (PMID 28603674, 2017). "We undertook this by analysing the expression of NA markers that we characterised in Xenopus AVNA development (Ascl1, Hand2, Phox2a and TH) in NB primary tumours, using publicly available microarray data." (PMID 25786414, 2015). "Prophylactic and therapeutic vaccination with murine TH cDNA or TH minigenes was able to protect against tumor growth after delivering plasmid DNA by oral gavage of attenuated S. thyphimurium to the mice." (PMID 21197271, 2010). "There are various treatment options available to manage the effects of catecholamine hypersecretion, including alpha-blockers, beta-blockers, calcium channel blockers, and tyrosine hydroxylase inhibitors, as well as surgical resection, radiofrequency ablation, and radiotherapy to the tumor." (PMID 39677999, 2024). "Similarly, the TH protein level was lower in nearly three quarters (74.24%) of the HCC tissue samples in contrast with the adjacent non-tumor tissue." (PMID 38610044, 2024). "According to TH IHC data and the RNAseq dataset in TCGA, the expression of TH in cancer tissues was higher than that in adjacent normal colon tissues, which was closely related to the tumor topography and tumor stages of patients with CRC." (PMID 37156838, 2023). "Furthermore, we identified eight hub genes (VSNL1, TH, PCP4, IGDCC3, RAD51AP2, MUC2, BUB1, and BUB1B) that promoted tumor progression and were associated with prognosis according to the Kaplan–Meier and ROC curve analyses." (PMID 36979826, 2023). "Furthermore, chronic stress upregulated the levels of TH, the rate-limiting enzyme of DA biosynthesis, suggesting that the DA generation and secretion by tumor cells increased locally after chronic stress indeed." (PMID 37415171, 2023). "In addition to the analysis of tyrosine hydroxylase immunoreactivity, the immunoreactivity of beta 2 adrenergic receptors was analyzed in pancreatic peritumoral tissue and tumor tissue." (PMID 37297000, 2023). "The dense immunostaining of ACTH, TH, dopamine-β-hydroxylase and the large tumor size with positive feedback loops may be correlated with high levels of ACTH and catecholamines in the circulation." (PMID 35854271, 2022). "Additionally, when comparing normal versus tumor tissues, TH, a rate-limiting enzyme in catecholamine biosynthesis, is upregulated in BC tissues, although its expression is yet substantially lower in relation to the other markers." (PMID 36428611, 2022). "Regarding the role of Th in tumor biology, it has been reported that chemical sympathectomy not only correlated with smaller tumors, but also significantly increased TH, neuropeptide Y, and glucocorticoid receptor gene expression in tumors from male C57BL/6 J mice." (PMID 33691777, 2021).
tumor (continued). "As expected, NB5t primary cells showed increased expression of mesenchymal genes (NT5E, ENG, ACTA2, MME, CD44, VIM or ALPL), while NB5t tumor sample expressed mostly neuronal genes (TH, ENO2, NCAM1, DDC or CHGB) reflecting the neuroblastic phenotype of stage 4/M NB tumors." (PMID 29163787, 2017). "However, histidine becomes relatively insensitive to the tumor extracellular environment when the pH is in the 6.5–7.2 range, thereby reducing the pH-dependent penetrating activity of TH." (PMID 28603674, 2017). "Furthermore, Lig3, Lig1 and PARP1 silencing also significantly blocked protein expression of neuronal developmental and NBL tumor markers (TH, Phox2b, TRKB) in differentiating NCSC-MYCN cells, quantified by Western blot analysis." (PMID 29238067, 2017). "The viable areas located at the periphery of the tumor contained numerous cells undergoing pyknosis, and the cytoplasm of these tumor cells was immunohistochemically positive for synaptophysin, tyrosine hydroxylase, and chromogranin A. The tumor cell nuclei were positive for SDHB." (PMID 27729064, 2016). "Our GD2 positive cell preparations were enriched in CD56+ and NB84+ mononuclear NB cells, showed the same genetic aberration as the primary tumor cells, and expressed NB-specific genes, such as TH, GD2 synthase, Phox2b, ELAV4 and DCX, at the same levels as primary tumor cells." (PMID 22253825, 2012). "Neuronal nuclear antigen, calcineurin, tyrosine hydroxylase and CD34 are other markers found in these tumours." (PMID 40013208, 2025). "TAAs in this study were selected from tyrosine hydroxylase (TH), Phox2B, Survivin, MAGEA1, MAGEA3, and PRAME, based on the highest expression in the patient tumor biopsy sample." (PMID 38791942, 2024). "In IHC and Western blotting analyses, we observed reduced TH protein abundance and decreased NE concentrations in iWAT (−48%) and aWAT (−56%) of LLC tumor-bearing IL-4ra-KO animals compared with WT controls." (PMID 35210363, 2022). "RT-PCR was chosen as analysis method to quantify minute numbers of tumor cells by measuring expression of PHOX2B, TH, and DDC." (PMID 34654486, 2021). "Experiments with spiking ratios of 1:1000 and 1:10,000 (PDX-1 cells to PBPCs) were performed, subsequently using RT-PCR to quantify tumor cells by measuring expression of PHOX2B, TH, and DDC." (PMID 34654486, 2021). "Further study has also figured out the co-expression of TH and DRD5 in tumor cells, demonstrating the vital roles of dopamine pathway in EC cells." (PMID 33898321, 2021). "To validate this finding, we performed additional IHC staining experiments on paraffin-embedded serial slices with similar tissue regions from the tumor specimen esPHEO_T3 using antibodies against CgA, ACTH, POMC, CRH, TH, and GAL." (PMID 34905486, 2021). "Even though expression of the dopamine synthesis genes TH and DDC can be identified in human tumors in the TCGA dataset, that information comes from bulk RNA-seq analysis of human tumor sections." (PMID 31822725, 2019). "All tumors maintained diffuse strong nuclear MYCN expression, and cytoplasmic labeling for markers used to characterize human NBL (TH, TRKB, and Chromogranin A) was generally focal to multifocal in small to moderate numbers of tumor cells." (PMID 29238067, 2017). "In this paper, by introducing electron donating groups to the histidine imidazole ring of TH, we developed a new type of acid-responsive CPP with a high sensitivity to the acidic tumor microenvironment and low toxicity under physiological conditions." (PMID 28603674, 2017). "Tyrosine hydroxylase labelling was extensive and present in all tumour cells, while CgA and NESP55 labelling was more limited and present in a subpopulation of tumour cells." (PMID 12771991, 2003). "A further IHC staining of tyrosine hydroxylase (TH) and SDHB was negative, suggesting the tumor was nonfunctional PGL with SDHx mutation." (PMID 36945070, 2023).
tumor (continued). "The best markers proved to be synaptophysin (highly specific, but occasionally also weakly staining connective tissue cells), and tyrosine hydroxylase (although often negative in primary HNPGL tumours and derived cultures)." (PMID 36178902, 2022). "Moreover, NSC11 and NSC20 tumor cells in the OB showed a higher number of contacts with MAP2+, TH+ and GABA+ neurons." (PMID 36482431, 2022). "Although many tumour cultures were strongly positive for tyrosine hydroxylase, many others were negative, indicating that this marker is also inconsistently expressed in tumour cell cultures." (PMID 36178902, 2022). "To characterize the role of PPM1D in tumor development, we constructed genetically engineered C57BL/6N mice overexpressing WIP1 through pronuclear injection of the human PPM1D gene controlled by the rat tyrosine hydroxylase (TH) promoter." (PMID 34771656, 2021). "We anticipate that a panel of markers, such as BPTF, TMCO3, CUX2, combined with classic markers: PHOX2B, TH, DCX, will prove valuable in a variety of clinical settings, including the assessment of tumor, drug resistance, residual disease monitoring and prediction of recurrence." (PMID 29467591, 2018). "TH(AGYLLGHINLHHLAHL(Aib)HHIL-NH2), a histidine-rich, cell-penetrating peptide with acid-activated pH response, designed and synthesized by our group, can effectively target tumor tissues with an acidic extracellular environment." (PMID 28603674, 2017). "At 4 weeks, ESCs were directly visualized with PKH26 costained tyrosine-hydroxylase (TH), not tumor growth." (PMID 28326106, 2017). "Ras-induced tumor progression was supported by MAPK-deficient, PI3K-competent H-Ras-tR, but not by R-Ras-tH, which showed weak activation of PI3K, and Ras tumor progression was blocked in all cases by inhibition of PI3K." (PMID 27239960, 2016). "We found that NB primary tumours have high expression of PHOX2A, HAND2 and TH." (PMID 25786414, 2015). "This approach appears feasible also for human NB cells since NB tumours express CTL-defined TAA, such as tyrosine hydroxylase (, MAGE-1 and 3, NY-ESO and ALK, and tumour-specific cytolytic T lymphocytes have been isolated from NB-bearing patients." (PMID 15150552, 2004). "Furthermore, neither ICI‐118551 nor SR59230A altered the density of TH+ nerve fibers within the tumor microenvironment, thereby excluding the possibility of a reduction in sympathetic nerve fibers." (PMID 40488319, 2025). "Tumor cells stained positive for tyrosine hydroxylase and negative for dopamine β hydroxylase." (PMID 37908587, 2023). "The tumor was positive for chromogranin A staining but negative for tyrosine hydroxylase." (PMID 36945070, 2023). "0.1 and 1 mg/kg Mab-TH could not reverse the trend of tumor growth, while complete inhibition was observed when 10 mg Mab-TH was given." (PMID 34669957, 2021). "Dopamine is converted from tyrosine by enzymes tyrosine hydroxylase (TH) and dopa decarboxylase (DDC), and a previous study found that CCA tumors had higher expression levels of TH and DDC compared to normal liver tissues detected by immunohistochemistry using 48 CCA tumor tissues." (PMID 32069926, 2020). "Moreover, we found that weak MAPK signaling was sufficient to support tumor initiation (R-Ras-tH), but not tumor progression." (PMID 27239960, 2016). "R-Ras-tH supported tumor initiation, but not tumor progression." (PMID 27239960, 2016). "Therefore, the abnormal elevation of plasma dopamine or the absence of TH immunoreactivity in PHEOs could indicate more aggressive biological behavior of the tumor." (PMID 33244312, 2020). "If the hormone levels cannot be alleviated entirely after the surgery (i.e., the levels of GH, TH, and TSH that are oversecreted before the surgery), and if there is no reduction or the disappearance of tumor on imaging, then radiotherapy or drug treatment is required." (PMID 36619586, 2022).
infection (40 papers, 2009 to 2025). The state of being infected such as from the introduction of a foreign agent such as serum, vaccine, antigenic substance or organism. "Infection has been associated with increased tyrosine hydroxylase expression, enhancing dopamine synthesis, while reducing dopamine D1 receptor, dopamine transporter, and Nurr1 expression, indicating impaired receptor signaling and reuptake." (PMID 41049318, 2025). "We observed that infection of Huh7 cells with DV at a MOI of 1 downregulated TH expression, which encodes a rate-limiting enzyme of the catecholamine biosynthesis as it produces the precursor L-Dopa." (PMID 35336971, 2022). "In one study, LPS injection into the striatum caused an approximately 48% reduction in TH+ neurons at 7 days post-infection, and the expression of Iba-1 in the striatum increased by 86%, whereas they increased by 36% in the 6-hydroxydopamine-treated group." (PMID 36278237, 2022). "Following infection, TH stained neurons undergo rapid loss of dendrites, cytosolic vacuolation and nuclear picnosis." (PMID 23251423, 2012). "We observed a modest reduction in TH-positive neurons detected in H. pylori-infected mice after 9 months of infection." (PMID 41430261, 2025). "To further confirm the infection of DA neurons, we analyzed both TH and NR4A2 positive cells as well as all cells." (PMID 38237586, 2024). "This dual-infection strategy allowed for optogenetic control of the VTA neurons that expressed TH (i.e., dopamine neurons)." (PMID 33794355, 2021). "A total of 14 days after the infection, triple staining against EGFP, TH, and MAP2 (microtubule associated protein 2) showed that many of the MLN-EGFP-infected AS expressed both TH, the specific marker of DA neurons, and MAP2, the marker of mature neurons." (PMID 34830023, 2021). "In order to investigate the effect of expression of tyrosine hydroxylase on potato susceptibility to infection, the HTZ lines were subjected to infection with Phytophtora infestans, a common and dangerous potato pathogen." (PMID 32784799, 2020). "Infection of primary SCG neurons with Cas9 coupled gRNAs resulted in the deletion of the zip-code in 44% of the TH loci as detected by genomic PCR analyses." (PMID 28630892, 2017). "At 18 and 21 days after infection, mice showed higher tyrosine hydroxylase (TH) mRNA levels in the adrenal gland compared with control groups." (PMID 27733201, 2016). "Infection of TH-Cre+ rats with Cre-dependent virus led to expression of transgenes in midbrain dopamine neurons." (PMID 25278845, 2014). "We observed a similar reduction of TH-positive neurons in H. pylori-infected mice in the therapy cohort, and no loss of neurons was observed in mice where infection was cleared with triple therapy." (PMID 41430261, 2025). "Thus, we propose that the TH complex can synergistically infect plant tissue to escape or suppress the plant’s basal resistance for their successful infection." (PMID 37035074, 2023). "Together, these observations raise the hypothesis that AaaH2 TH can modulate host dopamine levels during chronic infection, and that this modulation affects host behaviour." (PMID 29062106, 2017). "The ratio of co-labeled TH+ neurons produced by CAV is much higher than by RV-infection." (PMID 29251597, 2017). "Therefore the parasite has increased expression of its tyrosine hydroxylase during brain and muscle cyst-forming stages of infection." (PMID 19277211, 2009). "Importantly, the TH complex could alter the expression of microRNAs (miRNAs) in tobacco to negatively regulate the plant defense responses associated with individual TSWV and HCRV and then promote their successful infection in plant tissue." (PMID 37035074, 2023). "The results showed efficient infection of dopaminergic neurons in the SNpc, as evidenced by GFP expression in tyrosine hydroxylase (TH)-positive cells." (PMID 29311685, 2018).
infection (continued). "Infection of adenovirus expressing both WT and WT-CL1 α-syn led to the degeneration of the TH neuronal terminal in the striatum (F = 14.82; p<0.0001, Two way ANOVA)." (PMID 22701661, 2012). "The number of tyrosine hydroxylase (TH)- and phosphorylated α-Syn (Ser-129)-positive cells following α-Syn PFF injection significantly decreased in Fabp3−/− mice and markedly increased by AAV-GFP/FABP3 infection." (PMID 32210174, 2020). "Because some retrogradely labeled neurons were not TH-positive/dopaminergic we used a combinatorial retrograde infection approach that targets opsin expression specifically to dopamine projection neurons." (PMID 29950562, 2018). "Similarly, using a dual infection strategy, injected the VTA of rhesus monkeys with a mixture of the Cre-dependent ChR2 optogenetic activator (pAAV5-DIO-Ef1α-ChR2(h134)-EYFP) and a virus expressing Cre attached to a tyrosine-hydroxylase (TH) promoter (AAV2/9-rTH-PI-Cre-SV40)." (PMID 33794355, 2021). "We also tested the infection of tyrosine hydroxylase (TH) neurons in the substantia nigra pars compacta (SNc) by stereotactically injecting WT and WT-CL1 α-syn to the medial forebrain bundle (MFB) and found that these viruses could effectively infect TH neurons." (PMID 22701661, 2012). "Indeed, Tg infection increases the level of dopamine but not that of serotonin and norepinephrine, indirectly via the release of inflammatory cytokines, but mostly directly via the presence in its genome of genes coding for phenylalanine hydroxylase and tyrosine hydroxylase." (PMID 34085752, 2021). "Six to 10 days post-infection, the cultures were treated with or without 10 μM TMP for 4 days and triple-stained for tyrosine hydroxylase (TH) to identify DA neurons, GFP to identify transduced cells, and HA to identify levels of DD-Akt(E40K)." (PMID 29920520, 2018). "Injection of AAV9-SLR and AAV9-NSS resulted in a larger number of tdTomato+/tyrosine-hydroxylase-positive (TH+) neurons in SNc than WT-AAV9 (AAV9-SLR: p=0.0001; AAV9-NSS: p=0.0001), whereas injection of WT-AAV2 and AAV-RGD resulted in no retrograde infection to SNc." (PMID 30136928, 2018). "However, only one study has reported retrograde infection of unmyelinated nonpeptidergic [NP; equivalent to the isolectin B4 (IB4) binding population of sensory neurons] or tyrosine hydroxylase-positive unmyelinated C-fiber low-threshold mechanoreceptive (c-LTMR/TH+) sensory neurons." (PMID 28951448, 2017).
neurodegenerative disease (22 papers, 2010 to 2024). A disorder of the central nervous system characterized by gradual and progressive loss of neural tissue and neurologic function. "Dopamine synthesis can be promoted by TH through hydroxylation of tyrosine to L-DOPAThese results support that thicremonone could be an effective compound for neurodegenerative disease, and this effect can protect the brain against PD risk." (PMID 27409674, 2016). "Before the discovery of Trofinetide, GPE demonstrated modulatory effects on neurons and certain CNS enzymes (ChAT, GAD, NOS, and tyrosine hydroxylase) and was claimed to treat neurodegenerative diseases." (PMID 37568516, 2023). "Our data shows that the PA diet regulated the expression levels of α-syn, TH, dopamine and serotonin, which are all key proteins and neurochemicals involved in the pathogenesis of neurodegenerative diseases." (PMID 30127714, 2018). "It has previously been shown that TH-positive nerve terminals within the striatum are reduced in transgenic mice overexpressing α-synuclein, and D2R is downregulated in some neurodegenerative diseases." (PMID 20386702, 2010). "Moreover, a decrease in TH activity has also been discussed in other neurodegenerative diseases, such as AD and PD." (PMID 35885023, 2022). "In neurodegenerative disease, GSH is often exhausted, leading to oxidative stress and decreased in the tyrosine hydroxylase (TH) activity, which was the early step in dopamine synthesis." (PMID 33092139, 2020). "DAT+/TH+ monocyte populations in AD patients are indistinguishable from healthy controls, leading us to conclude that increased numbers of monocytes expressing markers of dopamine signaling are not general to all neurodegenerative diseases." (PMID 35672374, 2022).